S100A4 (S100 calcium binding protein A4)
Diseases named in the same sentence as S100A4 in open-access papers (continued):
Sharing a sentence is not in itself a finding about the gene and the disease.
pulmonary disease (10 papers, 2014 to 2025). "S100A4 has also been linked to various diseases besides tumor, such as cardiac fibrosis and hypertrophy, kidney fibrosis and pulmonary disease." (PMID 35305619, 2022). "Multiple regression analysis revealed significant association between S100A4 serum levels, pulmonary disease activity (β = 0.369; P = 0.002), LD (β = 0.345; P = 0.005) and severity of dysphagia (β = −0.250; P = 0.033) in the whole myositis patient group." (PMID 25359220, 2014). "S100A4 has been implicated in the development of several lung diseases." (PMID 37873538, 2023). "In this context, association between S100A4 levels and pulmonary disease activity may be of clinical significance." (PMID 25359220, 2014). "Various studies in recent years focused on the S100A4 function in lung diseases, showing researchers’ interests on this protein." (PMID 37026957, 2023). "It is necessary to focuses on relative studies, and make a comprehensive understanding of S100A4 in common pulmonary diseases." (PMID 37026957, 2023). "S100A4 is a protein that is well‐known for its involvement in pulmonary diseases." (PMID 36799806, 2023). "These two findings suggested a link between S100A4 and lung function in pulmonary diseases." (PMID 35379204, 2022). "In patients with DM, S100A4 serum levels correlated moderately with MYOACT (r = 0.46; P = 0.004) and pulmonary disease activity (r = 0.41; P = 0.011)." (PMID 25359220, 2014).
acute myeloid leukemia (9 papers, 2019 to 2025). Acute myeloid leukemia (AML) is a group of neoplasms arising from precursor cells committed to the myeloid cell-line differentiation. "Some studies have also shown that bone marrow mesenchymal stem cell-derived exosomes (BM-MSC-exos) can upregulate the expression of S100A4 to promote the proliferation of acute myeloid leukemia (AML) cells and enhance the resistance of AML cells to cytarabine." (PMID 36705798, 2023). "In acute myeloid leukemia cells, the overexpression of PRAME correlates with the decreased expression of Hsp27 (heat shock protein 27), S100A4, and p21 at the transcription levels." (PMID 38132219, 2023). "Consistent with this, a different study showed that extracellular S100A4 promotes MDSC expansion and suppression of T cell proliferation and activation in the context of acute myeloid leukemia (AML)." (PMID 40078995, 2025). "S100A4 has been shown to promote acute myeloid leukemia (AML) survival and S100A8 is considered as a prognostic marker for AML." (PMID 34485305, 2021).
autoimmune disease (9 papers, 2013 to 2025). A disorder resulting from loss of function or tissue destruction of an organ or multiple organs, arising from humoral or cellular immune responses of the individual to their own tissue constituents. "S100A4 is a Ca-binding protein regulating cell growth, survival and motility, and is associated with malignancies, as well as with various fibrotic, inflammatory and autoimmune diseases." (PMID 32021963, 2020). "Whether increased Treg‐mediated immunoregulation could explain the deficit in IL‐17 production and lower susceptibility to autoimmune disease observed in S100A4‐deficient animals remains to be explored." (PMID 26734465, 2015). "Review of the recent literature shows that S100A4 function in the immune system plays several key roles in the progression of cancer, fibrosis, and autoimmune diseases." (PMID 40078995, 2025). "Significant upregulation of S100A4 has been detected in other autoimmune diseases, such as idiopathic inflammatory myopathies and fibrostenosing Crohn’s disease." (PMID 29204268, 2017). "We and others have recently demonstrated increased expression of S100A4 at local sites of inflammation in several chronic inflammatory and autoimmune diseases, including muscle tissue from patients with idiopathic inflammatory myopathies." (PMID 25359220, 2014). "In a separate study of Sjogren’s syndrome, a long-term autoimmune disease, S100A4 signaling via olfactory ecto-mesenchymal stem cell-derived (OE-MSC) exosomes promoted IL-6 production in MDSCs via TLR4 signaling, which led to activation of the JAK2/STAT3 pathway." (PMID 40078995, 2025). "The role of S100A4 has already been demonstrated in several autoimmune disorders." (PMID 32021963, 2020). "Although S100A4 protein was initially studied in malignancy, there are several reports demonstrating increased amounts of S100A4 in patients with various inflammatory and autoimmune diseases." (PMID 25359220, 2014). "Therefore, one can only speculate about the possible effect of S100A4 depletion on the bone formation in the conditions of experimentally induced autoimmune disease." (PMID 32021963, 2020). "Our current result provides novel information about extracellular matrix remodeling by linking S100A4 to TAA, and supports the hypothesis that aortic aneurysm and autoimmune disease share common degenerative features." (PMID 23922901, 2013).
cervical carcinoma (9 papers, 2012 to 2025). A carcinoma arising from either the exocervical squamous epithelium or the endocervical glandular epithelium. "Decreased E-cadherin levels and overexpression of S100A4 have been associated with cervical cancer formation." (PMID 36982551, 2023). "The combined gain of S100A4 and loss of membrane E-cadherin in cervical cancer tends to confirm its link with an unfavorable prognosis." (PMID 32290283, 2020). "In bulky stage (IB-IIA) cervical cancer, elevated S100A4 in stromal cells enhances chemotherapy sensitivity." (PMID 40093000, 2025). "For these reasons, this study evaluated the effect of supernatants from cervical cancer cell lines (HeLa and SiHa) in the expression of vimentin, S100A4, αSMA, FAP, and MMP9 markers in an in vitro MSC-CAF model." (PMID 38606999, 2024). "The results indicated that DHM mediates cell migration through the regulation of S100A4 levels in cervical cancer cells." (PMID 36499426, 2022). "In conclusion, our study indicated that DHM inhibited cell migration by reducing the S100A4 expression through the ERK1/2/β-catenin pathway in human cervical cancer cell lines." (PMID 36499426, 2022). "In our study, the expressions of S100A4 mRNA and protein were significantly reduced in cervical cancer cells treated with arctiin compared with the control in a concentration-dependent manner." (PMID 35214097, 2022). "DHM regulates the translocating ability of β-catenin through the ERK1/2 pathway, thereby affecting the performance of the target S100A4 and ultimately inhibiting the migration ability of cervical cancer cells." (PMID 36499426, 2022). "In conclusion, our study revealed that arctiin inhibits cervical cancer cell migration and invasion through the suppression of S100A4 expression and the PI3K/Akt pathway." (PMID 35214097, 2022). "Our study revealed the anti-migration effects of arctiin on cervical cancer through the inhibition of S100A4 expression and the PI3K/Akt pathway." (PMID 35214097, 2022). "Taken together, these results suggest that arctiin inhibits cervical cancer cell migration and invasion through suppression of S100A4 and the PI3K/Akt pathway." (PMID 35214097, 2022). "They suggested that S100A4 could facilitate cervical cancer cell promotion and progression of cancer." (PMID 36982551, 2023). "We determined that DHM may inhibit the RNA and protein expression of S100A4 in human cervical cancer as well as S100A4 overexpression, which induces cell migration." (PMID 36499426, 2022). "Moreover, selective Akt induction by an Akt activator, SC-79, reverted cervical cancer cell migration and S100A4 protein expression, which were reduced in response to arctiin." (PMID 35214097, 2022). "Furthermore, we examined the effect of DHM on the crawling ability of human cervical cancer cells by regulating the S100A4 gene." (PMID 36499426, 2022). "Furthermore, silencing S100A4 by using small interfering RNA reduced cell migration, while overexpression of S100A4 mitigated the migration inhibition imposed by arctiin in cervical cancer cells." (PMID 35214097, 2022). "However, the role of S100A4 in the migration and invasion of cervical cancer is unclear." (PMID 35214097, 2022). "This study aimed to evaluate the protein expression of vimentin, S100A4, αSMA, FAP, and MMP9 in mesenchymal stem cells (MSC)-CAF cells, as well as in cervical cancer samples." (PMID 38606999, 2024). "To validate the RNA sequencing findings of S100A4, we conducted real-time PCR analysis and Western blotting assay and found that DHM inhibited S100A4 expression in cervical cancer cells in a concentration-dependent manner." (PMID 36499426, 2022). "Distinct intracellular localization of S100A6 and S100A4 was shown to be dependent on calcium concentrations in the MDA-MB231 metastatic epithelial breast adenocarcinoma cells and cervical carcinoma HeLa cells." (PMID 22727333, 2012).
cervical carcinoma (continued). "In addition, we investigated the protein levels of vimentin, S100A4, αSMA, FAP, MMP9, and Ki67 in different stages of cervical cancer." (PMID 38606999, 2024). "To determine whether cervical cancer cells conditioned media (SiHa and HeLa) can promote differentiation towards an MSC-CAF phenotype we evaluated vimentin, S100A4, αSMA, FAP, and MMP9 expression by immunofluorescence." (PMID 38606999, 2024). "In conclusion, we discovered that treating cervical cancer with DHM may inhibit cell migration and invasion through the regulation of S100A4 expression through the ERK1/2/β-catenin pathway." (PMID 36499426, 2022). "Furthermore, the expressions of S100P, S100A4, KRT7 and TGM2 were also induced by silencing of ACTL6A in cervical cancer cells." (PMID 34395295, 2021).
fibrosis (9 papers, 2009 to 2025). the formation of excess fibrous connective tissue in an organ or tissue in a reparative or reactive process. "The results reported in the preceding section indicated S100a4+ macrophage frequency was positively correlated with fibrosis in both the testis and epididymis." (PMID 41031892, 2025). "An increase in the proportion of S100a4+ cells is characteristic of many fibrotic conditions, and elevated serum S100a4 levels positively correlate with fibrosis clinically." (PMID 31124787, 2019). "Persistent proliferation of S100A4-positive fibroblasts has been associated with fibrotic diseases such as murine bleomycin-induced fibrosis, in which S100A4-positive cell numbers peak at 2-3 weeks and are still above baseline at 4 weeks." (PMID 19804646, 2009). "Hence, it is plausible that the release of TFs FOS, FOSB, and JUNB by C6 S100A4+ SMCs contributes to exacerbating cardiomyopathies, potentially through the induction of cardiac fibrosis and inflammation." (PMID 40717095, 2025). "Moreover, S100A4 and α-SMA’s generally distinct anatomic localizations and the differing pathological architecture associated with each (calcinosis versus fibrosis respectively), supports the idea that the two populations have distinct pathogenic roles." (PMID 37090702, 2023). "Elevated extracellular S100A4 level contributes to the development and progression of many fibrotic diseases, implying that extracellular S100A4 could be a potential therapeutic target for treating fibrosis pathologies." (PMID 32307910, 2020).
pulmonary hypertension (9 papers, 2017 to 2025). Increased pressure within the pulmonary circulation due to lung or heart disorder. "In humans, S100A4 is essentially absent in normal coronary arteries but is expressed in SMCs residing in pulmonary hypertension, atherosclerotic and restenosis coronary artery lesions, and S100A4 is considered a marker of these diseases." (PMID 37217870, 2023). "S100A4 also plays a role in pulmonary vascular remodeling, which is a result of pulmonary hypertension." (PMID 32218378, 2020). "The authors thus postulated that S100A4 was not implicated in the initial response to pulmonary hypertension but might exhibit functional relevance in advanced stages." (PMID 35053115, 2022).
Arthritis (8 papers, 2011 to 2024). Inflammation of a joint. "As disease activity in patients with RA correlated with S100A4 levels and anti-Jo-1-positive patients had increased S100A4 serum levels, we expected that presence of arthritis would contribute to the elevation of S100A4 in myositis patients." (PMID 25359220, 2014). "Indeed, we extracted novel genes such as S100A4, which is known to be involved in cancer metastatic progression but that results overexpressed in cartilage and synovium damaged by arthritis." (PMID 38491514, 2024). "Crosses with S100a4-cre resulted in milder skin lesions and moderate to severe arthritis." (PMID 32687504, 2020). "Thus, it can be hypothesised that in myositis, S100A4 may be associated with systemic activation of the immune system rather than with mechanisms driving arthritis during this debilitating disease." (PMID 25359220, 2014). "However, S100A4 levels were comparable between myositis patients with and without arthritis, which may point to a different pathogenesis of joint involvement in myositis patients compared to those with RA." (PMID 25359220, 2014).
Insulin resistance (8 papers, 2020 to 2024). Increased resistance towards insulin, that is, diminished effectiveness of insulin in reducing blood glucose levels. "Within this category, it is also important to highlight the S100A4 metastasis-associated protein, for which our research group have reported an association with insulin resistance and WAT dysfunction in prepubertal populations." (PMID 33803198, 2021). "Then the association between circulating S100A4 levels and insulin resistance in the two different cohorts was tested." (PMID 32128247, 2020). "S100A4 has been recently identified as an adipokine associated with insulin resistance (IR) in adult subjects with obesity." (PMID 32128247, 2020). "Further studies will be necessary to determine whether S100A4 can be a therapeutic target for obesity and the development of insulin resistance associated with this condition." (PMID 32128247, 2020). "Given that obesity has a major impact on both S100A4 levels and insulin resistance, the focus of the analysis was on subjects with obesity to avoid this confounding factor." (PMID 32128247, 2020). "As expected from previously published data (ref Arner), S100A4 levels were also elevated in our cohort of adult patients with severe obesity compared with normal‐weight controls and showed a correlation with insulin resistance." (PMID 32128247, 2020). "S100A4 has been identified as a biomarker for insulin resistance." (PMID 36276976, 2022). "Additionally, serum levels of S100A4, S100A8/S100A9, S100A12, and S100B correlate with insulin resistance/T2D, metabolic risk score, and fat cell size." (PMID 35328627, 2022). "S100A4 is a differentially methylated marker of insulin resistance in obese children." (PMID 33923831, 2021). "In this study, our hypothesis was that S100A4 would be elevated and directly correlated to insulin resistance in children with obesity as well as in adults." (PMID 32128247, 2020). "In subjects with obesity, S100A4 levels were associated with homeostatic model assessment‐insulin resistance (HOMA‐IR) in adults (βstd = .42, P = .008) but not in children (βstd = .12, P = .356)." (PMID 32128247, 2020). "HMGB1 released by necrotic adipocytes interacts with RAGE, inducing pro-inflammatory cytokines and ROS;S100A4, S100A8/A9, and S100B induce inflammation, interacting with RAGE;AGE accumulation in adipose tissue may contribute to obesity-associated insulin resistance." (PMID 34204735, 2021). "Surprisingly, the association between S100A4 and insulin resistance was not present in children." (PMID 32128247, 2020). "In conclusion, our human data demonstrate for the first time that S100A4 circulating levels are higher in children with obesity compared with normal‐weight individuals but do not correlate with insulin resistance as in adult subjects." (PMID 32128247, 2020). "The limitations of this study include the lack of adipose tissue samples in children to analyse the molecular mechanisms involved in the elevation of S100A4 and the lack of correlation with insulin resistance." (PMID 32128247, 2020).